CDKN1B (cyclin dependent kinase inhibitor 1B)
Description:
Important regulator of cell cycle progression. Inhibits the kinase activity of CDK2 bound to cyclin A, but has little inhibitory activity on CDK2 bound to SPDYA. Involved in G1 arrest. Potent inhibitor of cyclin E- and cyclin A-CDK2 complexes. Forms a complex with cyclin type D-CDK4 complexes and is involved in the assembly, stability, and modulation of CCND1-CDK4 complex activation. Acts either as an inhibitor or an activator of cyclin type D-CDK4 complexes depending on its phosphorylation state and/or stoichiometry.
Synonyms: KIP1; P27KIP1; CDKN4; MEN1B; MEN4
Tractability: Small molecule: a structure with a bound ligand is known. PROTAC: UniProt records ubiquitination sites on it; ubiquitination databases record sites on it; its protein half-life has been measured.
Gene: Protein-coding gene on chromosome 12 (12,685,498 to 12,722,373, forward strand). Ensembl gene ENSG00000111276.
Subcellular location: Nucleus; Cytoplasm; Endosome
Subcellular location (Human Protein Atlas): Centrosome; Nucleoplasm; Basal body; Cytosol; Primary cilium; Primary cilium transition zone
Pathways (Reactome):
Cell Cycle: Cyclin A:Cdk2-associated events at S phase entry; Cyclin D associated events in G1; Cyclin E associated events during G1/S transition; SCF(Skp2)-mediated degradation of p27/p21
Signal Transduction: AKT phosphorylates targets in the cytosol; Estrogen-dependent nuclear events downstream of ESR-membrane signaling; PTK6 Regulates Cell Cycle; RHO GTPases activate CIT
Cellular responses to stimuli: DNA Damage/Telomere Stress Induced Senescence; Senescence-Associated Secretory Phenotype (SASP)
Disease: Constitutive Signaling by AKT1 E17K in Cancer; Defective binding of RB1 mutants to E2F1,(E2F2, E2F3)
Gene expression (Transcription): FOXO-mediated transcription of cell cycle genes
Immune System: FLT3 Signaling
Gene Ontology:
Molecular function: cyclin binding; cyclin-dependent protein kinase regulator activity; cyclin-dependent protein serine/threonine kinase inhibitor activity; molecular adaptor activity; molecular function inhibitor activity; protein binding; protein kinase binding; protein kinase inhibitor activity; protein phosphatase binding; protein-containing complex binding; ubiquitin ligase activator activity; ubiquitin protein ligase binding; protein-folding chaperone binding
Biological process: autophagic cell death; cellular response to lithium ion; negative regulation of cell growth; negative regulation of cell population proliferation; negative regulation of vascular associated smooth muscle cell proliferation; nuclear export; positive regulation of protein catabolic process; regulation of cell cycle; regulation of cell cycle G1/S phase transition; regulation of cyclin-dependent protein serine/threonine kinase activity; regulation of G1/S transition of mitotic cell cycle; cellular senescence; G1/S transition of mitotic cell cycle; heart development; negative regulation of cardiac muscle tissue regeneration; negative regulation of epithelial cell proliferation; negative regulation of mitotic cell cycle; positive regulation of DNA replication; negative regulation of growth; regulation of mitotic cell cycle phase transition; signal transduction
Cellular component: Cul4A-RING E3 ubiquitin ligase complex; cytoplasm; cytosol; nucleoplasm; nucleus; endosome
Genetic constraint (gnomAD): Loss-of-function variants: 7 observed, 16.36 expected, observed/expected ratio (o/e) 0.43, 90% interval 0.24 to 0.8. The synonymous counts are far from expectation, so gnomAD's model fits this gene poorly and the ratio says little. Missense variants: 337 observed, 277.67 expected, observed/expected ratio (o/e) 1.21, 90% interval 1.11 to 1.33. Synonymous variants: 149 observed, 113.9 expected, observed/expected ratio (o/e) 1.31, 90% interval 1.14 to 1.5.
Gene-disease validity (ClinGen):
ClinGen rates the evidence that CDKN1B causes each of these diseases.
multiple endocrine neoplasia type 4 (autosomal dominant): Definitive. Multiple endocrine neoplasia type 4 (MEN4) is a very rare form of MEN, an inherited cancer syndrome, characterized by parathyroid and anterior pituitary tumors, possibly associated with adrenal, renal, and reproductive organ tumors.
hereditary nonpolyposis colon cancer (autosomal recessive): Limited.
Cancer hallmarks: suppression of growth (promotes); invasion and metastasis (suppresses); invasion and metastasis (promotes); tumour promoting inflammation (suppresses); change of cellular energetics; angiogenesis (suppresses); genome instability and mutations (suppresses); escaping programmed cell death (suppresses); escaping programmed cell death (promotes)
Homologues: Orthologues: chimpanzee CDKN1B (100% identical), macaque CDKN1B (98% identical), guinea pig CDKN1B (94% identical), dog CDKN1B (93% identical), pig CDKN1B (92% identical), rabbit CDKN1B (89% identical), mouse Cdkn1b (87% identical), rat Cdkn1b (86% identical), zebrafish cdkn1bb (38% identical), zebrafish cdkn1ba (36% identical). Paralogues in human: CDKN1C (30% identical), CDKN1A (20% identical).
Diseases named in the same sentence as CDKN1B in open-access papers:
CDKN1B is named in the same sentence as 326 diseases in open-access papers, as found by Europe PMC text mining. Sharing a sentence is not in itself a finding about the gene and the disease. The quoted sentences say what the papers report.
breast cancer (178 papers, 1999 to 2025). A primary or metastatic malignant neoplasm involving the breast. "In breast cancer (BC) research, uc.183, uc.110, and uc.84 inversely correlate with miR-221 and are implicated in the regulation of CDKN1B expression." (PMID 41552009, 2025). "Our study also found that reduced CDKN1B expression was linked to more aggressive tumor characteristics and poorer survival rates due to disease progression in breast cancer patients." (PMID 38248731, 2023). "The molecular processes driving carcinogenesis and the clinicopathological variances associated with CDKN1B expression in breast cancer remain incompletely understood." (PMID 38248731, 2023). "Among these, mutations in CDKN1B have been shown to occur at a frequency of 2.8% in breast cancer patients." (PMID 38248731, 2023). "This investigation revealed the underlying mechanism of CDKN1B expression in breast cancer by understanding the anticancer immune responses associated with these gene sets." (PMID 38248731, 2023). "Particularly, CDKN1B represents one of the 18 most significantly mutated genes in luminal breast cancer, a subtype accounting for more than 60% of all breast cancers." (PMID 33316141, 2021). "In fact, decreased expression or mislocalization of CDKN1B is associated with unfavorable outcomes in various solid tumors, including breast cancer." (PMID 32929377, 2020). "CDKN1B had been observed to be significantly down-regulated in breast cancer tissues and associated with increasing tumor grade, mitosis, poor overall and disease-free cancer survival." (PMID 31763681, 2020). "Up-regulation of CDKN1B significantly inhibited proliferation, invasion, caused cell cycle arrest in G1 and induced apoptosis of human breast cancer cells." (PMID 31763681, 2020). "Our data in Cdkn1b knock out ACI rat support a role for p27 as a key regulator of quiescent hormone-responsive luminal progenitors associated with breast cancer risk." (PMID 30893315, 2019). "Here we show that genetic deletion of Cdkn1b in ACI rats susceptible to estrogen-induced mammary tumors decreases the relative fraction of Cd49b+ luminal progenitors identifying p27 as a key regulator of the proliferation and pool size of these cells." (PMID 30893315, 2019). "Mutations in p27 gene, CDKN1B, have been reported for luminal breast cancer, prostate adenocarcinoma and, particularly frequent, small intestine neuroendocrine tumors and, again, the C-terminal domain is the most frequently mutated region." (PMID 30976290, 2019). "The rational for generating a Cdkn1b knockout in rats was in part due to the closer relatedness of estrogen-dependent mammary tumors in rats to human breast cancers and that germline mutations of Cdkn1b cause MEN syndrome in rats." (PMID 30893315, 2019). "By genome-wide screening of reverted xenograft tumours we demonstrated that treatment of luminal breast cancer cells with oocyte extracts induces cell cycle arrest associated with upregulated expression of CDKN1B (P27) and reduction of RB phosphorylation." (PMID 29662623, 2018). "Mutations of CDKN1B in luminal breast cancer occur, in more than half of the cases, in the C-terminal portion of the protein, suggesting that tumor suppressive activities are present in this region." (PMID 28377607, 2017). "In particular, we focused on luminal breast cancer (LBC) that is the breast cancer subtype with the highest frequency of CDKN1B mutations and chose the MCF-7 cell line as a validated model of LBC." (PMID 28377607, 2017). "It is interesting to note that, at least in MEN syndrome, breast cancer, intestine neuroendocrine tumors and prostate cancer, the CDKN1B gene (encoding for p27) is frequently mutated in the C-terminal portion of the protein." (PMID 27579539, 2016). "This is exemplified by the analysis of the breast cancer dataset, from which the well-known but rarely mutated cancer genes CDKN1B (7 mutations out of 772 samples), KRAS (6 mutations) and MEN1 (5 mutations) were identified." (PMID 25903787, 2015).
breast cancer (continued). "Recent studies on the association of CDKN1B with breast cancer have identified CDKN1B as a driver gene that is almost exclusively mutated in luminal breast cancer (LBC) and found that it is enriched in mutations leading to loss of function in metastatic breast cancer patients." (PMID 38248731, 2023). "Understanding the molecular mechanisms underlying CDKN1B dysregulation and its impact on breast cancer progression is important to improve treatment strategies for breast cancer by developing potential therapeutic targets and identifying its role as a prognostic marker." (PMID 38248731, 2023). "In addition, CDKN1B has been recognized as a potential driver mutation in the development of breast cancer and prostate cancer." (PMID 35355569, 2022). "Evidence has shown that miR‐222‐3p could target several genes, and a relationship of miR‐222‐3p‐targeted CDKN1B has been implicated in breast cancer cells 29 and vascular smooth muscle cells 30, but this relationship has not been reported in NP cells." (PMID 30984546, 2019). "The V109G polymorphism of the p27 gene CDKN1B (rs2066827), examined by polymerase chain reaction analysis of tumour specimens, was associated with shortened disease-free survival in a subset of patients with infiltrating metastasis-free breast cancer." (PMID 18507837, 2008). "Thus, CDKN1B/p27 may impact both breast cancer risk and disease progression by regulating the proliferation of hormone-responsive progenitors." (PMID 30893315, 2019). "However, other genetic variants of CDKN1B have been associated with other tumours such as prostate cancer 34, oral squamous cell carcinoma 35, invasive epithelial ovarian cancer 36, high‐grade breast tumour 37 and lymph node metastasis in breast cancer." (PMID 28667701, 2017). "CDKN1B alterations have been reported in breast cancers and prostate carcinomas as well as in small intestine neuroendocrine tumors (SI-NETs), where mutations of CDKN1B represent one of the most frequent gene alterations." (PMID 39936980, 2025). "High CDKN1B expression levels in breast cancer correlated with high lymphocyte infiltration signature scores and increased CD8+ T cells, both of which were associated with improved prognosis in breast cancer." (PMID 38248731, 2023). "In our study, the cohort of 456 breast cancer patients was stratified into two categories using the optimal cut-off for CDKN1B expression." (PMID 38248731, 2023). "We analyzed the effect of CDKN1B expression on breast cancer survival using the gradient boosting machine (GBM) algorithm." (PMID 38248731, 2023). "Our findings provide insights into the potential role of CDKN1B as a biomarker for survival prediction and immunotherapy response in breast cancer." (PMID 38248731, 2023). "Our results also revealed that CDKN1B expression was significantly lower in breast cancer tissues than in normal mammary gland tissues." (PMID 38248731, 2023). "By in vitro drug screening, we found that BMS-345541 effectively reduced breast cancer cells with low CDKN1B expression." (PMID 38248731, 2023). "The CDKN1B-induced survival model improvement suggests that CDKN1B is a potent prognostic factor in breast cancer." (PMID 38248731, 2023). "In in vitro drug screening, BMS-345541 demonstrated efficacy as a therapeutic targeting of CDKN1B, effectively impeding the growth of breast cancer cells characterized by low CDKN1B expression." (PMID 38248731, 2023). "In this study, our objective was to examine the correlation between CDKN1B expression levels and clinicopathological factors as well as survival rates in breast cancer patients." (PMID 38248731, 2023). "High CDKN1B expression predicts sensitivity to hormone therapies and chemotherapy in luminal breast cancer patients, while its downregulation predicts resistance to radiotherapy and anti‐ERBB2 therapies." (PMID 37039257, 2023).
breast cancer (continued). "CDKN1B was found to primarily participate in anticancer functions, exhibiting lower expression levels in breast cancer tissue in comparison to normal breast tissue." (PMID 38248731, 2023). "Further studies are needed to evaluate the efficacy of these treatments in specific subsets of breast cancer patients based on CDKN1B expression." (PMID 38248731, 2023). "In this study, we used GBM analysis to investigate the influence of CDKN1B expression on breast cancer survival." (PMID 38248731, 2023). "First, the detailed molecular mechanisms and signaling pathways through which CDKN1B influences the clinical outcomes of breast cancer, using our bioinformatics approach and in silico analysis, need to be experimentally validated." (PMID 38248731, 2023). "We investigated the clinicopathologic factors, survival rates, immune cells, gene sets, and prognostic models according to CDKN1B expression in 3794 breast cancer patients." (PMID 38248731, 2023). "Based to the CPTAC dataset, CDKN1B protein levels were reduced in tumor tissues from breast cancer and clear cell RCC compared to controls, but they did not statistically differ from colon cancer, lung adenocarcinoma, ovarian cancer, and UCEC, respectively." (PMID 37432583, 2023). "BMS-345541 effectively inhibited the growth of breast cancer cells in 50 cell lines, especially those with low CDKN1B expression (p = 0.012)." (PMID 38248731, 2023). "In vitro drug screening showed that BMS-345541 reduces the growth of breast cancer cells with low CDKN1B expression." (PMID 38248731, 2023). "In this study, we demonstrate that miR-575 also targets CDKN1B, inducing tamoxifen resistance in ER+ breast cancer." (PMID 32929377, 2020). "In tamoxifen-treated patients with breast cancer, the tamoxifen-induced downregulation of miR-575 expression upregulates CDKN1B expression, leading to increased tamoxifen response." (PMID 32929377, 2020). "Together, these results indicate that miR-575 decreases tamoxifen sensitivity by regulation of CDKN1B in ER+ breast cancer cells." (PMID 32929377, 2020). "This possibility is also supported by frequent lesions in the RB/E2F pathway in breast cancer, including loss of RB1, CDKN1B (encoding p27), and CDKN2A as well as amplification of CCND1." (PMID 32985974, 2020). "A recent study found that under propofol treatment, the number of apoptotic cells was increased via inhibition of the miR‐24/cyclin‐dependent kinase inhibitor 1B (p27) signalling pathway in breast cancer." (PMID 32596964, 2020). "Recent studies have demonstrated that CDKN1B can be genetically inactivated, particularly in luminal breast cancer, prostate cancer, and small intestine neuroendocrine neoplasms." (PMID 32684843, 2020). "Recent works have demonstrated that CDKN1B can be genetically inactivated and this occurs particularly in sporadic luminal breast cancer, prostate cancer and small intestine neuroendocrine tumors." (PMID 30065701, 2018). "We validated by real-time qPCR the increased expression of CDKN1A and CDKN1B in PC and breast cancer cells." (PMID 29381681, 2018). "In human luminal breast cancer (LBC) p27kip1 is frequently down-modulated and CDKN1B, p27Kip1 gene, sporadically mutated." (PMID 28377607, 2017). "FOXO3A, another member of the forkhead box O family of transcription factors is also regulated by miR-96 expression in breast cancer, which results in subsequent downregulation of CDKN1B and CDKN1A." (PMID 24260486, 2013). "Previously, we have shown that Id1/3-PA7 regulates the expression of CDKN1A and CDKN1B in a dose-dependent manner in breast cancer cells MCF-7 and MDA-MB-231, which contain the homozygous deletions of the gene CDKN2A." (PMID 20842131, 2010).